VIM (vimentin)
Diseases named in the same sentence as VIM in open-access papers (continued):
Sharing a sentence is not in itself a finding about the gene and the disease.
breast carcinoma (continued). "Furthermore, in breast cancer, GFPT2 induces EMT by increasing vimentin expression via HBP activation and enhances cell invasion and proliferation." (PMID 38888874, 2024). "We previously reported that TWIST1 induces the transcriptional activation of mesenchymal genes such as VIM (Vimentin) and SNAI2 (Snail 2) but induces the transcriptional repression of epithelial genes such as CDH1 (E-cadherin) and ESR1 (ERα) in breast cancer cells." (PMID 38893094, 2024). "Kaempferol induces the cell cycle at the G2/M phase in MDA-MB-453 breast cancer cells and reverses the EMT process in gastric, ovarian, and breast cancer cells by modulating key markers such as E-cadherin, Smad2/4, TGF-β, N-cadherin, vimentin, and Snai1." (PMID 39275063, 2024). "Moreover, we investigated the presence of CD45+ CTCs in CRC, breast cancer (BC) and NSCLC patients by detecting the epithelial-mesenchymal markers EpCAM, Vimentin, or abnormal expression of ERBB2, or CK." (PMID 38575583, 2024). "In the literature, it has been reported that the absence of E-cadherin and vimentin protein expression and the aberrant expression of N-cadherin protein led to more invasive breast cancer." (PMID 38451194, 2024). "For this reason, we decided to evaluate whether Brazilin influence the expression of EMT markers such as E-cadherin, vimentin, and Twist, the secretion levels of MMP-2 and MMP-9 and the invasion of MCF7 and MDA-MB-231 breast cancer cells." (PMID 38737746, 2024). "In addition, knockdown of ZNF‐148 downregulated the expression of N‐cadherin and vimentin, which are involved in epithelial‐mesenchymal transition (EMT) in breast cancer cells." (PMID 37909239, 2023). "Finally, immunohistochemistry analysis showed that exosomes from cells transfected with si-circRHOT1 prompted an increase in the expression of E-Cadherin and N-cadherin and induced a decrease in Vimentin, thus inhibiting the EMT of breast cancer cells." (PMID 37924099, 2023). "In conclusion, our results suggest a mechanism by which FRMD3 interacts with vimentin and ubiquitin ligase UBE3A through its ubiquitin-like domain to promote proteasome degradation of vimentin, thereby exerting a unique function of FRMD3 in breast cancer progression." (PMID 36631457, 2023). "In conclusion, our findings showed that lncRNA ZEB2‐AS1 up‐regulation could act on breast cancer onset and development through ZEB2, vimentin, and E‐cadherin dysregulation." (PMID 37088469, 2023). "This study compared the expression of vimentin, α-SMA, MMP1, PDGF and CD95 in the two types of breast cancer to assess which factors play a greater role in the process of local recurrence in each type of breast cancer." (PMID 38046195, 2023). "Furthermore, high-dose VC effectively blocked TGF-β1-induced breast cancer cell invasion as well as reversed the TGF-β1-induced downregulation of E-cadherin and upregulation of vimentin in these cells." (PMID 38067361, 2023). "Interestingly, compared with CTCs in metastatic patients, the DTCs in the bone marrow of early HER2-positive breast cancer patients presented increased expression of stem cell markers such as ALDH1, CAV1 and VIM." (PMID 36765527, 2023). "Western blot assay revealed that HSPB1 overexpression led to decreased expression of epithelial markers (E-cadherin) and increased expression of mesenchymal markers (Fibronectin, N-cadherin, Vimentin), highlighting the significant effect of HSPB1 on regulating EMT in breast cancer cells." (PMID 37454220, 2023). "Previous studies have shown that DHT-activated AR interacts with demethylase LSD1 to repress E-cadherin transcription and upregulate vimentin transcription in the ER and AR positive MCF7 breast cancer cells, leading to EMT that increases cell migration and invasion." (PMID 35960413, 2022).
breast carcinoma (continued). "OC treatment increased the tumor expression of epithelial markers (E-cadherin) while decreasing the expression of mesenchymal markers (vimentin), as well as decreasing the activation of Met and HER2 receptors and the serum levels of CA 15-3 human breast cancer marker." (PMID 35056792, 2022). "Based on the qPCR and Western blot analyses, we selected MCF-7, a simple epithelial breast carcinoma cell line devoid of endogenous vimentin to recapitulate the EMT process and ectopically expressed the full-length vimentin (pLPChygro-FV) or the control vector (pLPChygro-CV)." (PMID 36552797, 2022). "They found that in breast cancer cells and mouse tumor tissues with high expression of LINC00665, E-cadherin was downregulated, and Vimentin and N-cadherin were significantly upregulated, indicating that LINC00665 induced EMT-like phenotype in breast cancer cells." (PMID 35356290, 2022). "Our team has also recently reported that upregulation of α-tubulin (TUB), vimentin (VIM) and detyrosinated α-tubulin (GLU) in CTCs derived from breast cancer patients could be deployed as useful biomarkers to identify cancer cells with an aggressive phenotype." (PMID 35207643, 2022). "The cytoskeletal protein vimentin is considered a major epithelial to mesenchymal transition (EMT) factor responsible for cell migration and integrity and contributes to an aggressive phenotype in breast cancer." (PMID 36127671, 2022). "In our study, it was discovered that BHLHE41 overexpression largely enhanced the levels of BHLHE41 and E-cadherin but repressed the levels of HIF-1α, N-cadherin, vimentin, and MMP9 in hypoxia-induced CC cells, which was consistent with the report of BHLHE41 in breast cancer." (PMID 35615737, 2022). "Furthermore, in silico analysis of the Cancer Genome Atlas (TCGA) and METABRIC data sets from thousands of patients with breast cancer revealed that CD47 expression positively correlates with SNAI1 and Vimentin." (PMID 35575054, 2022). "High-grade carcinomas present higher numbers of cells positive for vimentin, nuclear β-catenin, and CD44, compared to low-grade carcinoma and benign lesions, suggesting that the breast cancer cell de-differentiation process could be related to EMT." (PMID 36669020, 2022). "In accordance with this biological event, it has been shown that tumor cells from buds from breast cancer show phenotypic features, such as the lack of E-cadherin expression and expression of vimentin." (PMID 33669393, 2021). "Immunostainings of lungs from opioid-treated mice bearing breast cancer xenografts further demonstrated that the observed metastases are highly positive for Vimentin, a further mesenchymal marker, and negative for cleaved Caspase-3." (PMID 33465556, 2021). "Furthermore, metformin treatment of two primary breast cancer cells MBCDF and MBCD17 downregulated mesenchymal signature genes vimentin and SNAIL and inactivated NFKB and STAT3 signaling pathways in response to IL-6." (PMID 35052372, 2021). "Indeed, vimentin has been described to interact with MAP2K4 to activate AKT pathway, leading to increased proliferation and invasion of breast cancer cells." (PMID 34203746, 2021). "In vivo monitorization of different mesenchymal markers (FSP1 and Vimentin) using different breast cancer models demonstrated that the EMT process does not contribute to lung metastasis development." (PMID 35052683, 2021). "Following treatment with PFD, we found that PFD significantly reduced the migration of an invasive type of breast cancer cells and CAFs, and significantly decreased the expression of EMT marker vimentin, stemness marker CD44, and YAP1 in CAF-tumor spheroids at the protein level." (PMID 34680267, 2021). "Together with the IHC score for HRD1 and Vimentin in matched breast cancer samples, these results suggest a significant inverse relationship between HRD1 and Vimentin expression in patients with breast cancer." (PMID 33530981, 2021).
breast carcinoma (continued). "Overexpressed in several aggressive breast cancer cell lines where HRD1 was verified to be significantly downregulated, Vimentin plays a pivotal role at the very center of the EMT process through which the increased cellular invasion and migration lead to the metastasis of breast cancer." (PMID 33530981, 2021). "To further investigate the potential molecular mechanism by which CT45A regulates breast cancer cell migration, we monitored the alteration of EMT markers, including N-cadherin and vimentin, two well-characterized mesenchymal markers, and E-cadherin, a well-known epithelial marker." (PMID 34503444, 2021). "We aimed to study the impact of EMT-related markers on a breast cancer cohort and specifically analyze the involvement of Snail, Twist, ZEB1, N-cadherin, Vimentin, GRHL2, E-cadherin, and EpCAM and their respective outcome on both immune infiltration of the TME and clinicopathological features." (PMID 34680248, 2021). "Calycosin significantly increased the expression of E-cadherin (epithelial cell biomarker) and decreased the expression levels N-cadherin and Vimentin (mesenchymal cell biomarkers) as well as CD147, MMP-2, and MMP-9 (pro-metastatic proteins) in the breast cancer cells." (PMID 34096887, 2021). "In fact, while Tyr acts on the β-catenin and TGF-β pathways in breast cancer, in the same cancer model OC modulates the HER2/MET pathway and reduces vimentin by significantly inhibiting the recurrence rate, which is what makes these compounds exploitable in post-surgery therapy." (PMID 33513799, 2021). "To further examine the impact of loss of PRLR expression on the differentiation state of the HR+ MCF-7 breast cancer cells, we used immunofluorescence confocal microscopy to assess the expression pattern of the mesenchymal and EMT markers, vimentin and the transcription factor Snail." (PMID 33446633, 2021). "On the contrary, vimentin, an intermediate filament protein characteristically upregulated in cells undergoing EMT, plays a key role in the motility and migration of breast cancer cells as it is also highly expressed at the wound edge in mammary epithelial cells and breast cancer cells." (PMID 34769002, 2021). "Similarly, nuclear β-catenin expression and increased LEF1 levels are reported in migratory, vimentin-expressing oral squamous cancer cells (OSCC) and breast cancer cells." (PMID 34638929, 2021). "Vimentin is an intermediate filament of basal-like and mesenchymal cells and is considered as a canonical marker and an important regulator of epithelial mesenchymal transition (EMT) in several types of cancers including breast cancer." (PMID 34203746, 2021). "Indeed, vimentin regulates gene expression and is required for EMT induced by Ras, Slug and TGFβ in breast cancer cells." (PMID 34203746, 2021). "There are also reports of SAHA promoting EMT through the HDAC8/FOXA1 axis in triple-negative MDA-MB-231 and BT-549 breast cancer cells, in which SAHA upregulated the mesenchymal markers N-cadherin, vimentin, and fibronectin and downregulated E-cadherin expression." (PMID 34502112, 2021). "For instance, miR-138-5p inhibits metastasis and EMT by targeting vimentin in breast cancer and renal cell carcinoma, and a novel feedback loop exists between miR-124-3p and the TGF-β pathway driving NSCLC metastasis." (PMID 32575745, 2020). "In human breast cancer specimens, TNC is co-expressed with the mesenchymal marker vimentin." (PMID 32817625, 2020). "We bring here further support to this narrow relationship linking TF and vimentin by exploring RNA expression public databases that revealed a positive correlation between the two molecules both on nonmetastatic and metastatic breast cancers." (PMID 32152404, 2020). "Therefore, breast-cancer derived CTC cell lines expressing E/M hybrid phenotypes (cytokeratins 8/18, vimentin, CD44) have been shown to metastasize after tail-vein or intracardiac injection." (PMID 32575608, 2020).
breast carcinoma (continued). "In this study, LINC00665 reduced the expression of E-cadherin and induced the expression of N-cadherin and vimentin, whereas knockdown of endogenous LINC00665 produced the opposite effects in breast cancer cells, suggesting that LINC00665 is an inducer of EMT in breast cancer." (PMID 31907362, 2020). "We further confirmed that knockdown of PHB reduced the protein level of EMT markers VIMENTIN and FIBRONECTIN and inhibited the migration of the MDA‐ MB‐231 breast cancer cell line which supports the important role of PHB‐involved HIRA complex in increasing mesenchymal gene expression." (PMID 32865342, 2020). "Furthermore, we propose that CTGF is a versatile regulator in breast cancer and facilitates SPARC, LOX, ZEB1, VIM and FN1 expression changes." (PMID 33087801, 2020). "And Snail can also inhibit the expression of other epithelial genes such as Claudin1 and Muc1 and promote the expression of other mesenchymal genes such as fibronectin, MMP9 and vimentin, which activates EMT and is related to tumor metastasis, recurrence and poor prognosis in breast cancer." (PMID 32028981, 2020). "The infiltrating breast carcinomas characterized by a higher number of vimentin-positive breast cancer cells frequently showed no or rare positivity for nBMP-2." (PMID 32498363, 2020). "Firstly, using IHC to investigate established EMT breast cancer biomarkers, we demonstrated that the MCF-7 RR and ZR-751 RR cell lines exhibited downregulated E-cadherin expression and upregulated vimentin, N-cadherin and SNAIL expression compared to their parental cells." (PMID 32851022, 2020). "In agreement with previous studies, we found that Nic elevated Snail and Vimentin O-GlcNAcylation, which could stabilize these EMT regulators and increase breast cancer cell invasion." (PMID 31019204, 2019). "Finally, we observed that knocking down Vimentin suppressed p-PI3K, p-AKT, c-JUN, c-Myc, and Cyclin D1(CCND1), N-cadherin and restored E-cadherin expression in MAP2K4-overexpressed breast cancer cells." (PMID 31761784, 2019). "The pronounced secretion of TGFβ1 by CAFs in breast cancer promotes an aggressive phenotype in tumor cells also through direct activation of EMT, with decreased expression of E-CADHERIN and over-expression of VIMENTIN, Fibronectin1 (FN1), MMP2 and MMP9." (PMID 30927908, 2019). "We then investigated whether STIM2 influences EMT in breast cancer cells by determining expression levels of two markers of EMT, E-cadherin and vimentin." (PMID 31464639, 2019). "Since MTF down-regulated Vimentin and SNAIL levels in mesenchymal breast cancer primary cells, a model of EMT induction using IL-6, which is a well-known EMT inducer in several types of tumors including breast cancer, was established." (PMID 31337349, 2019). "Co-expression of Vimentin and keratin in MCF-7 breast cancer cells increases cell invasiveness." (PMID 31080560, 2019). "Mammary carcinomas (n = 119) of female or female-spayed pet rabbits were immunostained for cytokeratin AE1/AE3, vimentin, smooth muscle actin (SMA), and calponin; and percentages of non-neoplastic myoepithelial cells (ME cells) and calponin-positive neoplastic cells were determined." (PMID 31569405, 2019). "The research of TNFAIP6, DHRS3, ASS1, RIPK4, VIM, and CD200 in breast cancer may indicate that those genes may play a crucial role in the development of breast cancer bone metastasis." (PMID 30918839, 2019). "Moreover, MAP2K4 interacts with Vimentin further accelerating cell proliferation, migration, and invasion, and co-expression of MAP2K4 and Vimentin was found to be an unfavorable factor in breast cancer prognosis." (PMID 31761784, 2019). "CAF-educated monocytes exhibited strong immune suppression unlike NF-educated monocytes and enhanced the motility/invasion of breast cancer cells in addition to increasing the expressions of epithelial–mesenchymal transition (EMT)-related genes and vimentin protein in cancer cells." (PMID 30816272, 2019).
breast carcinoma (continued). "In the current study, we demonstrated that CAF-educated monocytes increased breast cancer cell invasion as well as the expressions of EMT-related genes and vimentin protein significantly, while decreasing E-cadherin protein expression; in contrast to NF-educated monocytes." (PMID 30816272, 2019). "Similarly, over-expression of miR-129-5p in the breast cancer cell line MCF-7 was found to significantly induce E-cadherin and suppress N-cadherin and vimentin expression." (PMID 31649488, 2019). "We report here elevated levels of EMT markers (vimentin and ZEB1/2) and reduced levels of EMT-regulating miR-200 (miR-200b and miR-200c) in ER-positive breast cancer cells, MCF-7, that were resistant to tamoxifen, in contrast with the naïve parental MCF-7 cells that were sensitive to tamoxifen." (PMID 31827114, 2019). "The expression levels of E-cadherin, vimentin, DDR1, DDR2, α2 integrin, α11 integrin, COL1A1, MT1-MMP, BIK, estrogen receptor α, progesterone receptor, and HER2 mRNAs in 58 breast cancer cell lines were analyzed in silico, by using the Broad-Novartis Cancer Cell Line Encyclopedia (CCLE) database." (PMID 31130862, 2019). "In breast cancer cells overexpressing Zfas1, the EMT-related markers, such as E-cadherin expression, were upregulated while N-cadherin and vimentin expressions were downregulated, indicating that the effects of Zfas1on cell migration and invasion were partially associated with the EMT process." (PMID 31231466, 2019). "On the other hand, western blotting analysis also indicated that BA downregulated the levels of N-cadherin and vimentin as the mesenchymal markers, while increased E-cadherin which is an epithelial marker, validating the EMT inhibition effects of BA in breast cancer cells." (PMID 31531187, 2019). "Partial NKILA silencing showed no major effect on EMT markers in either breast cancer cell line, however, miR‐103 delivery in HMECs dramatically attenuated the expression of Vimentin and E‐cadherin, while increasing N‐cadherin expression levels." (PMID 31282094, 2019). "Expression of VIM, CDH1, CDH2, PLS3, CXCR4, CD44 and NANOG have been found in healthy controls and the maximal expression levels of these genes were the threshold beyond which CTCs-EBF of breast cancer patients were considered positive." (PMID 30634453, 2019). "The tumor differentiation, lymphatic and distant metastasis, and the levels of E-cadherin and Vimentin were correlated with upregulation of Dock1 in breast cancer, but age, tumor size, or hormonal level were not." (PMID 31528235, 2019). "MMPs, ADAMs, HES1/2, HEY1, c-Myc, CD44, EpCAM and Vimentin (downregulation of E-cadherin) engage in survival, stemness, EMT, invasion, ECM degradation/remodeling, angiogenesis, intravasation/extravasation, and metastatic colonization in breast cancer." (PMID 31694640, 2019). "This EMT process was partly verified in breast cancer cells with counterevidence, in which HDGF overexpression stimulates the cell invasion and metastasis by decreasing E-cadherin expression and increasing Vimentin expression." (PMID 29300772, 2018). "In the metastatic breast cancer cell line MCF-7, re-expression of miR-21 increased cell motility and invasion with concomitant decreased E-cadherin and increased mesenchymal markers such as Vimentin and N-cadherin." (PMID 30361805, 2018). "However, a previous study showed that treatment of OE inhibits the upregulation of SMAD4 and SNAIL2 (Slug), TCF4, VIM (Vimentin), FN (fibronectin) and SERPINE1 genes in a breast cancer cell line and MDCK cells." (PMID 29940929, 2018). "Co-exposure to TGF-β1 and E2 resulted in a trend of increased expression of VIM and ACTA2 compared to TGF-β1 alone which is consistent with one study that reported E2 promoted reversible EMT-like transition and collective motility in breast cancer cells." (PMID 30165855, 2018).